ANKRD26 (ankyrin repeat domain 26)
Diseases named in the same sentence as ANKRD26 in open-access papers (continued):
Sharing a sentence is not in itself a finding about the gene and the disease.
leukemia (6 papers, 2013 to 2024). A malignant (clonal) hematologic disorder, involving hematopoietic stem cells and characterized by the presence of primitive or atypical myeloid or lymphoid cells in the bone marrow and the blood. "Point mutations in the 5′UTR of ANKRD26 have shown to result in familial thrombocytopenia 2 and leukemia predisposition, mainly mediated by the derepression of ANKRD26 due to insufficient RUNX1/FLI1 complex binding." (PMID 34502524, 2021). "Mutations in 5′UTR of ANKRD26, leading to ANKRD26-RT, disrupt this regulation, resulting in the persistent expression of ANKRD26, which leads to impaired platelet biogenesis and an increased risk of leukemia." (PMID 39791724, 2024). "Next-generation sequencing (NGS) targeting 172 leukemia- and lymphoma-related genes identified ANKRD26-p.Asn267Ser, PTPN11-p.Glu76Lys, CIITA-p.His1119Asn and FAT1-p.Phe765Tyr mutations." (PMID 35912172, 2022).
thrombocytopenia 2 (6 papers, 2016 to 2025). An autosomal dominant disorder caused by mutation(s) in the ANKRD26 gene, encoding ANKRD26 protein. "Mutations in the 5′-untranslated region (5′-UTR) of ankyrin repeat domain-containing protein 26 (ANKRD26) are associated with hereditary thrombocytopenia 2 (THC2)." (PMID 40170493, 2025). "In fact, single nucleotide substitutions in the 5’ UTR of human ANKRD26 are known to be functionally relevant; they modify ANKRD26 expression and are the genetic cause of familial thrombocytopenia 2 (THC2)." (PMID 38369744, 2024).
platelet disorders (5 papers, 2021 to 2025). "ANKRD26-related thrombocytopenia (ANKRD26 RT) is an autosomal dominant thrombocytopenia caused by a single nucleotide substitution in the ANKRD26 gene, characterized by quantitative and qualitative platelet disorders and an increased risk of MDS and AML." (PMID 38203823, 2024). "Genes involved in germline predisposition and preexisting platelet disorders include RUX1, ANKRD26, and ETV6." (PMID 36534659, 2022).
Insulin resistance (4 papers, 2012 to 2019). Increased resistance towards insulin, that is, diminished effectiveness of insulin in reducing blood glucose levels. "In addition, perturbations of ANKRD26 gene expression and methylation correlate to the TG/HDL-C ratio, a recently identified mark of cardio-metabolic risk and of insulin resistance." (PMID 31801613, 2019).
ciliopathies (3 papers, 2020 to 2025). "Gaining mechanistic insights into the function of mammalian TALPID3 and ANKRD26 would be critical for understanding the pathogenesis underlying corresponding ciliopathies." (PMID 32366837, 2020). "Here, by using both the C. elegans genetic model and mammalian cells, we uncovered that the ciliopathy protein TALPID3 associates with TFs and characterized ANKRD26 as a TF component." (PMID 32366837, 2020). "The conserved coordination between TALPID3 and ANKRD26 in regulating proper formation of the ciliary gate is likely the core function of TALPID3 and a major pathway involved in TALPID3 deficiency-induced ciliopathy phenotypes." (PMID 32366837, 2020).
Fanconi anemia (2 papers, 2017 to 2021). Fanconi anemia (FA) is a hereditary DNA repair disorder characterized by progressive pancytopenia with bone marrow failure, variable congenital malformations and predisposition to develop hematological or solid tumors. "Patients with Diamond–Blackfan anemia, Fanconi anemia, dyskeratosis congenita, and familial thrombocytopenia/AML and MDS predisposition syndromes due to RUNX1, ANKRD26 gene mutations, and GATA2-associated MDS/AML met these criteria." (PMID 28690869, 2017).
lymphoid neoplasm (2 papers, 2021 to 2023). A neoplasm composed of a lymphocytic cell population which is usually malignant (clonal) by molecular genetic and/or immunophenotypic analysis. "Finally, the possible contribution of germline mutations, including DDX41, RUNX1, ETV6, ANKRD26, and POT1, which have been associated with the occurrence of both myeloid and lymphoid neoplasms, is an intriguing point to be explored in future studies." (PMID 34733777, 2021).
Macrothrombocytopenia (2 papers, 2013 to 2017). "Finally, variants in the 5′ UTR of ANKRD26 (MIM: 610855) were reported to result in non-syndromic macrothrombocytopenia in 201121 after an initial erroneous report that variants in the neighboring gene ACBD5 (MIM: 616618) were responsible." (PMID 28669401, 2017). "MYH9-RD, mono and biallelic BSS and ITGA2B/ITGB3-RT are currently classified as inherited macrothrombocytopenias, while ANKRD26-RT has been reported to have platelets of normal size." (PMID 23617394, 2013).
bleeding disorders (1 paper, 2015). "A handful of the candidate defects were present in genes that had previously been associated with platelet bleeding disorders, including P2RY12, VPS33B, GATA1, ANKRD26, HPS1, VWF, and LYST22." (PMID 25556537, 2015).
childhood leukemia (1 paper, 2022). An acute or chronic leukemia that occurs during childhood. "Genetic alterations affecting the process of megakaryopoiesis, such as MYH-9, ETV6, RUNX1, and ANKRD26 variants, have been reported to cause leukemic progression and are especially related to the genetic predisposition of childhood leukemia." (PMID 36534659, 2022).
gray platelet syndrome (1 paper, 2022). Gray platelet syndrome (GPS) is a rare inherited bleeding disorder characterized by macrothrombocytopenia, myelofibrosis, splenomegaly and typical gray appearance of platelets on Wright stained peripheral blood smear. "Syndromic IPDs are associated with defects in cells, tissues, organs, or the development of neoplastic disease (e.g., Wiskott–Aldrich syndrome, Hermansky–Pudlak syndrome, gray platelet syndrome (GPS), or variant of ANKRD26)." (PMID 36430862, 2022).
lung squamous cell carcinoma (1 paper, 2024). "For lung squamous cell carcinoma, 11 genes were causally related, comprising COPA, NCSTN, U91328.19, GABBR1, IER3, HLA-DQB1-AS1, HLA-DQB2, ANKRD26, PKD2L1, PSMA4 and RAD51C." (PMID 38834983, 2024).
nutritional deficiency (1 paper, 2025). "At the A + U extreme, IMPACT and ANKRD26 are two genes that mediate cellular adjustments to nutritional deficiency." (PMID 40341320, 2025).
thrombotic thrombocytopenic purpura (1 paper, 2025). "The only clue linking ANKRD26 to pathogenesis of thrombotic thrombocytopenic purpura (TTP) is the higher frequency of mutations in the ANKRD family identified in patients with iTTP than in unaffected controls." (PMID 40170493, 2025).
cancer (6 papers, 2022 to 2025). A tumor composed of atypical neoplastic, often pleomorphic cells that invade other tissues. "Each of these cases also carried other germline mutations (PBRM1, C7 and MYH9, BRCA1, ANKRD26) of which BRCA1 and ANKRD26 are cancer predisposition genes." (PMID 37869077, 2023). "In addition, we detected variants in several known cancer predisposition genes (eg, ETV6, RUNX1, ANKRD26, and IKZF1), highlighting the importance of long-term surveillance and genetic counseling in IPDs with potential malignant transformation risk." (PMID 40488176, 2025).
hematological malignancies (4 papers, 2021 to 2025). "This suggests that mutations in the 5′-UTR of ANKRD26 alone are not sufficient to cause malignancy transformation, and other genetic abnormalities or environmental factors are needed to trigger the development of hematological malignancy." (PMID 40170493, 2025).
tumor (3 papers, 2021 to 2024). "Nonetheless, we found 46 genes that carried either genomic or transcriptional alterations in all three resistant tumor groups, including 8 genes (Parp3, Gstm1, Il18, Padi4, Dnmt3b, Psrc1, Rif1, and Ankrd26) involved in DDR." (PMID 37209095, 2023).
ANKRD26 also shares sentences with these, for which no sentence is quoted: myelodysplastic syndrome (4 papers); Chronic Myeloid Leukemia (3); diabetes (2); acquired thrombocytopenia (1); acute leukemia (1); acute promyelocytic leukemia (1); Bernard-Soulier syndrome (1); Bloom syndrome (1); bone marrow failure syndrome (1); cardiovascular disease (1); chronic lymphocytic leukemia (1); dyskeratosis congenita (1); dysplasia (1); Evans syndrome (1); gastritis (1); genetic disorders (1); heart failure (1); hematological neoplasms (1); kidney diseases (1); Li-Fraumeni syndrome (1); lymphoma (1); neutropenia (1); Shwachman-Diamond syndrome (1); Stroke (1); thrombosis (1); Wiskott-Aldrich syndrome (1).